IL6 (interleukin 6)
Diseases named in the same sentence as IL6 in open-access papers (continued):
Sharing a sentence is not in itself a finding about the gene and the disease.
Cachexia (continued). "Cytokines produced by immune or tumor cells, including TNF-α, IL-1β, and IL-6, have been proven to cause muscle atrophy in cachexia patients and animal models." (PMID 34093209, 2021). "Tumor derived pro-inflammatory cytokines including TNF, interferon-γ (IFN-γ), and several interleukins (IL-6, IL-1β) have been associated with the development and progression of cachexia." (PMID 34621740, 2021). "Several studies have linked cachexia to increased plasma levels of proinflammatory cytokines such as interleukin (IL) 1β, IL6, tumor necrosis factor-alpha (TNF-α), and interferon-gamma (IFN-γ)." (PMID 32547603, 2020). "Cancer-related cachexia or weight loss associates with various biomarkers of systemic inflammation, including but not limited to, select cytokines (e.g., interleukin (IL)–6 and IL-8) and C-reactive protein (CRP) concentrations." (PMID 32371869, 2020). "Yet, high constitutive levels of circulating IL-6 caused suppression of muscle protein synthesis at the initial stage of cachexia in a different murine model." (PMID 32195193, 2020). "We analyzed expression of several transcripts associated with cachexia, including C‐reactive protein (Crp), insulin‐like growth factor 1 (Igf‐1), IL‐1ß (Il‐1b), IL‐6 (Il‐6), and TNF (Tnf)." (PMID 32039522, 2020). "Given the dual role of IL-6, in cachexia high plasma levels of this myokine cause a decrease in muscle weight, cause muscle atrophy and an increased cathepsin level." (PMID 32775472, 2020). "The IL-6/STAT3 signaling pathway induces a loss of muscle mass in experimental cachexia models via two pathways, where on the one hand, STAT3 phosphorylation leads to activation of hepatic acute phase protein gene expression." (PMID 33158194, 2020). "Specifically, the ApcMin/+ mouse, a commonly used model of spontaneous colorectal cancer and associated cachexia, displays a significant reliance on the cytokine Interleukin‐6 (IL‐6) for the development of cachexia." (PMID 33063952, 2020). "Conversely, under pathologic conditions, such as aging and chronic inflammation disease-associated cachexia, the plasma levels of IL-6 increase persistently, promoting muscle atrophy primarily by inducing catabolic pathways." (PMID 32493731, 2020). "Further evidence about involvement of procachectic cytokines in fat loss during cachexia was found for IL-6." (PMID 32195193, 2020). "In mice, IL-6 administration induces cachexia and IL-6 blockade reverses muscle loss in cancer cachexia models." (PMID 33291708, 2020). "For instance, inflammatory markers like tumor necrosis factor-alpha (TNF-α) and interleukin-6 (IL-6) are linked to cachexia and known to contribute to muscle loss and lipid wasting by increased protein breakdown and adipocyte lipolysis." (PMID 31717736, 2019). "Elevated IL-6 levels in cancer patients are associated with cachexia, and IL-6 inhibitors have been suggested as possible treatment adjuncts in cancer patients in order to prevent this catabolic effect." (PMID 31540528, 2019). "IL6 in particular has been functionally linked to cachexia, and is elevated in patients with cachexia-associated cancers." (PMID 31058816, 2019). "Given that IL-6 is released by myeloid cells including macrophages and myeloid-derived suppressor cells (MDSCs) associated with cachexia, we analyzed the proportions of macrophages and MDSCs in the spleen." (PMID 31717643, 2019). "Numerous inflammatory cytokines are involved in the etiology of cachexia, including tumor necrosis factor alpha, interleukin (IL)-6, IL-1 and interferon gamma indicating that systemic inflammation plays a central role in cancer-associated cachexia." (PMID 31466311, 2019). "IL-6-mediated cachexia has been shown to be associated with increased proteolytic activity in skeletal muscle cells." (PMID 30081609, 2018).
Cachexia (continued). "Previous studies showed that IL-6 or IL-6 receptor antibodies can counteract, at least in part, body weight loss, fat browning and/or muscle atrophy in mouse models of cachexia with contradicting effects on tumor progression." (PMID 29719601, 2018). "Results from early experiments demonstrated that muscles of mice that transgenically overexpressed IL-6 displayed a significant loss of muscle mass akin to cachexia." (PMID 30081609, 2018). "Interleukin-6 (IL6) affects development of cachexia, which is a major cause of cancer-related death." (PMID 30524272, 2018). "According to this line of reasoning, more frequent inflammation-associated cancers arise with a weakened TREG-mediated inhibitory loop with consequences of neutrophilia and elevated IL-6 heightening the risk of cachexia." (PMID 26933816, 2016). "In this sense, it has been demonstrated that endurance exercise ameliorates cachexia-related inflammation in a rodent model, causing a systemic effect that is also associated with adipose tissue and decreases IL-6 in mesenteric adipose tissue." (PMID 26508818, 2015). "Recent studies indicate that IL-6 is linked to glucose homeostasis in adipose tissue and it participates in the switch from white to brown fat tissue in cancer-induced cachexia." (PMID 25974216, 2015). "Chronic Poly I:C treatment, via activation of Tlr3 and the RIG-I-like receptors, results in the production of IL-6 and IFNγ that can, when provided chronically as a model for cachexia, lead to a progressive weight loss." (PMID 25856311, 2015). "In particular, the G-allele of the IL6-rs1800796 polymorphism was associated with decreased survival and increased susceptibility to cachexia in Chinese PDAC patients." (PMID 25238546, 2014). "The specific role of IL-6 in cancer associated cachexia and skeletal muscle wasting has been identified." (PMID 24877061, 2014). "Meanwhile, transplantation of IL-6-expressing Lewis Lung Carcinoma cells caused cachexia in mice, which then received either MR16-1 or 0.9% saline." (PMID 25010770, 2014). "In particular, IL-6 has been implicated in the development of cachexia in tumour-bearing rodent models and loss of adipose tissue in cancer patients as well as directly stimulating lipolysis in adults." (PMID 24667661, 2014). "In sum, our data suggest that SJDBT ameliorates cancer-associated anorexia/cachexia by regulating cytokines (IL-6 and MCP-1) and hormones (GLP-1 and PYY)." (PMID 24963216, 2014). "The weight loss observed in cancer patients, secondary to the inflammation-associated cachexia, mirrors the weight loss observed in the scorbutic mice with high IL-6 levels." (PMID 23175106, 2013). "Altered expression of proteins regulating mitochondrial biogenesis and fusion are early events in the initiation of cachexia regulated by IL-6, which precede the loss of muscle mitochondrial content." (PMID 22769563, 2012). "Further work is needed to understand the association between sedentary behavior and chronically high IL-6 levels, which are characteristics of late stage cachexia, on the processes regulating mitochondria loss during the progression of cachexia." (PMID 22769563, 2012). "Late stage cachexia in ApcMin/+ mice is also associated with a surge in circulating IL-6 and a reduction in volitional physical activity." (PMID 22769563, 2012). "Increased IL-6 levels are involved in metabolic and structural changes in muscle and in muscle loss during cachexia." (PMID 22908954, 2012). "Exercise is a potent method to increase oxidative capacity in skeletal muscle, and we have recently shown exercise can counteract muscle loss during IL-6-induced cachexia." (PMID 22769563, 2012). "We have previously reported inhibition of IL-6 signaling can attenuate the progression of cachexia and subsequent loss of muscle mass." (PMID 22769563, 2012).
Cachexia (continued). "Taken together, these findings suggest that administration of hochuekkito significantly decreased the serum level of IL-6 in the tumor-bearing mice and attenuated the metabolic alterations in muscle and fat tissues associated with cancer cachexia." (PMID 23326296, 2012). "Studies have found associations with cachexia and polymorphisms in IL-1-β, IL-10, IL-6 and IL-8 genes." (PMID 21934689, 2011). "Pro-inflammatory cytokine IL-6 has been implicated in the regulation of muscle wasting during cachexia in both humans and rodents." (PMID 21949739, 2011). "Cytokines, including Tumor Necrosis Factor (TNF)/cachectin, interleukin (IL)-1α, IL-1β, interferon-γ, and IL-6 have been implicated in cachexia both through experimental manipulation in mouse models and by association of serum levels in patients with cachexia." (PMID 21799891, 2011). "Cytokines that have been implicated in the development of cachexia include IL-6, IL-1, TNFα, and interferon-gamma (IFN-γ)." (PMID 21832306, 2011). "Some cytokines, including TNF-α, interleukin-1 (IL-1), IFN-γ, and IL-6 have been implicated in cachexia." (PMID 22185352, 2011). "The acute LCMV disease has characteristics of starvation that resemble both cachexia (TNF-α or IL-6-mediated wasting) and anorexia (appetite loss)." (PMID 19216742, 2009). "Interleukin 6 (IL-6), a mediator associated with cachexia in this tumour model, is detected at high levels both in the tumour tissues and in the circulating blood of mice bearing colon 26 tumour at the s.c. inoculation site." (PMID 10070867, 1999). "In many instances, locally produced IL-6 entered the peripheral circulation and caused systemic effects such as cachexia and tumor-associated syndromes (fever, increased erythrocyte sedimentation rate, increased serum C-reactive protein levels, hypoalbuminemia)." (PMID 40549756, 2025). "It is also interesting to note that TGFβ, IL1, and IL6 are associated with programmes in cancer cells that drive metastasis, which could potentially explain why metastatic disease is linked to cachexia more strongly than the presence of primary disease alone." (PMID 38898221, 2024). "Therefore, IL-6 has been proposed as one of the two most essential markers or pathogenic factors for cancer- and cardiac-induced cachexia." (PMID 38727319, 2024). "A targeted activation of IL-6 signaling may help burning off energy stored in fat as heat, and in turn, inhibiting cachexia-associated IL-6 synthesis may help to block pathological weight loss and improve life quality." (PMID 38474057, 2024). "Furthermore, several studies evaluated the effects of IL-6 inhibitors (such as Clazakizumab or Tocilizumab) on increased body weight but only few case reports ameliorated cancer-associated cachexia." (PMID 37173873, 2023). "While a very recent study reported that cachexia in PDAC is mediated by trans-signaling of tumor-derived IL-6 among tumor, muscle and fat tissue, others showed that circulating IL-6 levels correlate rather with advanced disease stage but less with weight loss and cachexia in PDAC patients." (PMID 36672405, 2023). "Adipose tissue is an important endocrine organ that releases a variety of factors which include cytokines (TNF-α, IL-6, IL-1β, IL-10, among many others) and adipokines which promote important systemic inflammation and are possibly associated with the pathogenesis of cachexia and cardiac cachexia." (PMID 35326490, 2022). "This systemic IL-6 spillover is considered a basis for paraneoplastic syndrome, which includes cachexia (loss of body weight), fever, enhanced erythrocyte sedimentation rate, and altered acute phase plasma protein levels (e.g., enhanced C-reactive protein levels and hypoalbuminemia)." (PMID 35406728, 2022). "Interestingly, single nucleotide polymorphisms in the IL-1, IL-6 and IL-10 genes have been associated with cachexia in gastrointestinal cancers." (PMID 36158184, 2022). "IL-6 has been implicated in the systemic inflammatory response of cachexia." (PMID 34822426, 2021).
Cachexia (continued). "Interleukin 6 (IL6) has long been associated with cachexia development in patients and C26 mice." (PMID 35008253, 2021). "Moreover, the overexpression of IL-6 induces loss of muscle mass in various models of cancer cachexia." (PMID 34944037, 2021). "To determine the relative functional significance of these inflammatory cytokines in CKD, we tested whether Il6, Tnfα or Il1β deficiency would affect the cachexia phenotype in CKD mice." (PMID 34302016, 2021). "Furthermore, muscle wasting correlated with mortality and murine IL-6, and human IL-6 associated with the greatest murine cachexia." (PMID 33851955, 2021). "In CRC-associated cachexia, a cooperation between TAMs and cancer cells (mainly IL-1R-positive cells) can be observed, leading to phenotypic differentiation of monocytes toward the “pro-inflammatory” type (up-regulation of IL-6, IL-12b, and IFN-γ)." (PMID 33557173, 2021). "While IL-6 is known to cause fat wasting in cachexia, more experimental evidence is needed to understand the interaction between cytokines in augmenting adipose wasting in cachexia." (PMID 33923976, 2021). "Indeed, administration of ActRII neutralizing antibodies to tumor-bearing mice effectively reduces circulating IL-6 levels and reversed muscle loss and other manifestations of cachexia." (PMID 33291708, 2020). "Increased levels of IL-6 also causes muscle and fat wasting in mouse models of cachexia." (PMID 33334063, 2020). "However, TNF-α and IL-6 levels remained increased in the serum of these animals, highlighting a possible indirect action of these cytokines in driving cachexia and adipose tissue loss through lipolytic mechanisms." (PMID 33329046, 2020). "Furthermore, poor-performance status and cachexia, associated with cytokines of IL-6 and TNF, are well known." (PMID 31426531, 2019). "Moreover, plasma levels of IL6 were significantly correlated to the degree of tumor progression and symptoms of cachexia (loss of lean mass, severe fatigue, and anorexia) in humans." (PMID 30072615, 2018). "We also found positive association between serum IL-6 and FFA in both early- and late-stage cachexia, suggesting IL-6 might induce weight loss in cancer cachexia by accelerating WAT lipolysis." (PMID 29338749, 2018). "The IL-6 signaling pathway has also been linked to muscle mitochondrial function with cachexia." (PMID 28785374, 2017). "From these reports the idea that IL-6 could be a good marker to predict the evolution of cachexia associated with cancer and could be employed in treatment strategies emerged." (PMID 26508818, 2015). "In addition, inflammatory response is associated with increased circulating levels of specific cytokines, such as IL-1, IL-6, IFNγ, TNFα, and acute-phase proteins that lead to hypermetabolism and weight loss in patients with anorexia and cachexia." (PMID 26504362, 2015). "It is important to note that although IL-6 has an important effect on the development of cachexia associated with cancer, IL-6 cannot be considered the only factor contributing to the breakdown of skeletal muscle and, consequently, to the development of cachexia." (PMID 26508818, 2015). "Features of cachexia such as hypogonadism (resulting in low testosterone) or systemic inflammation (associated with high IL-6) could influence such regenerative capacity." (PMID 24404136, 2014). "To investigate whether there is an association between cachexia and IL6-rs1800796, AKT1-rs1130233 and SELP-rs6136 polymorphisms, we performed genotyping using genomic DNA extracted from peripheral blood samples." (PMID 25238546, 2014). "In contrast to the acute effects of IL-6, inhibition of IL-6 signaling in ApcMin/+ mice in the initial stages of weight loss partially rescued the loss of testosterone and testes atrophy during the progression of cachexia." (PMID 24285707, 2013).
Cachexia (continued). "The increased production of IL-6 has been implicated in B-cell malignancies and could play a role in human and rodent cachexia, as suggested before by results obtained with anti-IL-6 mAb therapy." (PMID 22761662, 2012). "Future randomised trials with this group of agents should include prospective assessment of inflammatory markers such as IL-6 and other cytokines implicated in cachexia, as well as outcomes that may reveal benefits of skeletal muscle gain." (PMID 22510747, 2012). "Moreover, a Chinese research group recently published associations with cachexia and SNPs in the IL-6, IL-8 and IL-10 genes." (PMID 21934689, 2011). "Classically, elevated IL-6 has been implicated in muscle wasting diseases such as cachexia." (PMID 19554087, 2009). "Blood interleukin-6 can rapidly enter the AP to activate a subpopulation of the AP neurons and its associated network, and the silencing of interleukin-6-induced neuronal activation attenuates cachexia and hyperactivity to prolong the lifespan of tumor-bearing mice." (PMID 41118118, 2026). "The beneficial effect of IL6 on metabolism regulation is supported by animal models in which exogenous IL6 administration led to weight reduction and by treatment of patients with Castleman disease with anti-IL6 antibody receptor, which reversed disease-associated cachexia." (PMID 36986146, 2023). "Atrogin-1 is known to result in cachexia-induced muscle atrophy, and TJ-41 treatment ameliorates muscle weight loss in mouse cancer models together with decreased IL-6 production in macrophages, further suggesting that TJ-41 treatment might repress atrogin-1 in the cachexia-induced muscle atrophy." (PMID 36578084, 2022). "Different kinds of cancer cells are known to secrete IL-6, a candidate mediator of cachexia, and IL-6 levels correlate with weight loss in some cancer patients; moreover, increasing levels of IL-6 in tumor-bearing mice correlated with the development of cachexia." (PMID 34262449, 2021). "Thus, we tested whether activin A antagonism is able to reduce the systemic (serum) level of IL‐6 in tumour‐bearing animals and whether a putative reduction in IL‐6 level is associated with reversal of cachexia." (PMID 31436048, 2020). "The existence of convincing data with regard to the cachexia‐causing ability of both activin A and IL‐6 could be due to different mechanisms operating in different contexts and patients but could also be due to a functional relationship between activin A and IL‐6." (PMID 31436048, 2020). "Therefore, in the current study we investigated the association with cachexia and the prognostic value of the candidate functional polymorphisms IL6-rs1800796, AKT1-rs1130233 and SELP-rs6136 in a first cohort of 151 patients with locally-advanced or metastatic PDAC." (PMID 25238546, 2014). "Muscle atrophy has been described to occur in IL-6 transgenic mice, and inoculation of mice with Chinese hamster ovary tumor cells expressing IL-6 was found to be associated with body weight loss and hypophagia suggesting that IL-6 might be involved in the syndrome of cachexia." (PMID 24381940, 2013). "We hypothesized the altered expression of muscle proteins regulating mitochondria biogenesis, fission and fusion would be regulated by IL-6 in muscle at the onset of cachexia and precede mitochondrial content loss, which is most prominent during late stage cachexia." (PMID 22769563, 2012). "Ketogenic diet accelerates cachexia onset and shortens survival in IL-6-related cancer cachexia mouse models." (PMID 41526343, 2026). "IL-6 was initially identified as a cachexic factor approximately 30 years ago and continues to be a prominent focus of cachexia research." (PMID 41278737, 2025). "Traditional inflammatory markers including C-reactive protein (CRP), tumor necrosis factor-alpha (TNF-α), and interleukin-6 (IL-6) remain valuable indicators of the systemic inflammation driving muscle wasting, particularly in cachexia." (PMID 41220691, 2025).